CUL2 (cullin 2)
Diseases named in the same sentence as CUL2 in open-access papers (continued):
Sharing a sentence is not in itself a finding about the gene and the disease.
amebiasis (1 paper, 2018). A parasitic infectious disorder caused by amoebas. "While there is high linkage disequilibrium within this region leading to an associated block of sites, the numerous known eQTLs for CREM overlapped with our signals, while only one of the known eQTLs for CUL2 exhibited association with amebiasis." (PMID 30228239, 2018). "Expression quantitative trait loci (eQTL) analyses identified decreased CREM and likely not CUL2 to be associated with amebiasis." (PMID 30228239, 2018).
astrocytoma (1 paper, 2024).
bladder cancer (1 paper, 2013). "Indeed, cullin 2 (CUL2) and mesoderm development candidate 1 (MESDC1) were recently described as being targets of miR-574-3p in gastric and bladder cancer cells, respectively." (PMID 23626837, 2013).
Cachexia (1 paper, 2022). Severe weight loss, wasting of muscle, loss of appetite, and general debility related to a chronic disease. "How the CUL2–APPBP2–PRDM16 interaction is regulated in response to other pathophysiological cues, such as cachexia, hormonal cues and diet, is an important topic of future research." (PMID 35978186, 2022).
colon cancers (1 paper, 2016). "They identified CUL2 frameshift mutations in colon cancers and suggested that mutations inactivate the tumor suppressor function of CUL2 through HIF-1α proteolysis." (PMID 26983985, 2016).
diarrheal disease (1 paper, 2025). The condition of having at least three loose or liquid bowel movements each day. "The discovery that our identified CREM locus reference allele was associated with alterations in CREM-regulated gene expression but not changes in CCNY or CUL2 mRNA enabled us to ascribe the CREM locus reference allele phenotypes affecting diarrheal disease and undernutrition to CREM itself." (PMID 40576353, 2025).
dyslipidemia (1 paper, 2025). "The identification of these protein hubs may reflect underlying pathways involved in dyslipidemia (OSBPL10), beige fat biogenesis (CUL2), fatty liver disease and insulin resistance (PRTN3)." (PMID 40822952, 2025).
enterovirus infection (1 paper, 2022). "During enterovirus infection, the autoinhibitory NLRP1 N-terminal fragment is degraded by the ZER1/CUL2 and ZYG11B/CUL2 complexes." (PMID 36346242, 2022).
immune deficiency (1 paper, 2025). "In this study, we investigated the functional significance of Cul2 in the immune deficiency (IMD) signaling-mediated antimicrobial immune reactions in Drosophila melanogaster (fruit fly)." (PMID 40141268, 2025).
inflammatory bowel disease (1 paper, 2018). A spectrum of small and large bowel inflammatory diseases of unknown etiology. "The top association was on a haplotype spanning CUL2 and CREM on chromosome 10, a region that has previously been implicated with inflammatory bowel disease." (PMID 30228239, 2018).
liver cancer (1 paper, 2022). An epithelial or non-epithelial malignant neoplasm that arises from the liver. "Furthermore, both CUL2 and RBX1 have been shown to contribute to the ubiquitination and degradation of the tumour suppressor RHOB in liver cancer." (PMID 35664333, 2022).
lymph node metastasis (1 paper, 2022). "The association of plasma Circ-CUL2 with clinicopathological features was clarified, like age, gender, smoking status, histological classification, tumor size, lymph node metastasis and clinical stage." (PMID 35068326, 2022). "The results manifested that plasma Circ-CUL2 was extremely linked with clinical stage and lymph node metastasis, assuring that CirC-CUL2 was supposed to be a biomarker for NSCLC diagnosis and prognosis." (PMID 35068326, 2022).
malaria (1 paper, 2024). Malaria is a serious and sometimes fatal disease caused by a parasite that commonly infects a certain type of mosquito which feeds on humans. "To investigate the CRLs of human malaria parasite Plasmodium falciparum, we generated parasites expressing tagged P. falciparum cullin-1 (PfCullin-1), cullin-2 (PfCullin-2), Rbx1 (PfRbx1) and Skp1 (PfSkp1)." (PMID 38416790, 2024).
malignant renal cell carcinoma (1 paper, 2022). "In addition, CUL2, CDC42, GLUT1 and other proteins, which have been demonstrated to be critical in malignant renal cell carcinoma, were predicted to be downstream target proteins of microRNAs differentially expressed in PMAH patients compared with normal controls." (PMID 34986816, 2022).
oral cancer (1 paper, 2024). "Based on the gene specificity of selected genes modulated by anethole in Ca9-22 oral cancer cells, we found that two out of the 13 analyzed genes (CDKN3 and CUL2) were involved in the G1 phase & G1/S transition." (PMID 39689117, 2024).
osteosarcoma (1 paper, 2017). A usually aggressive malignant bone-forming mesenchymal neoplasm, predominantly affecting adolescents and young adults. "Among the other six Cullins, only CUL4A was slightly overexpressed (~1.4–1.7-fold induction) in osteosarcoma cells, but not the other five Cullins, including CUL1, CUL2, CUL3, CUL5 and CUL7." (PMID 28446751, 2017).
Sepsis (1 paper, 2025). Sepsis is defined as life-threatening organ dysfunction caused by a dysregulated host response to infection. "In summary, this suggests that MAF1 and CUL2 expression were dysregulated during BBB injury in sepsis." (PMID 39833662, 2025).
uterine tumors (1 paper, 2023). "Further search of the pan-cancer expression profile of CUL2 revealed that its expression was significantly higher in patients with uterine tumors than in normal patients." (PMID 37397007, 2023).
uveal melanoma (1 paper, 2003). A melanoma derived from melanocytes of the uveal tract. "ET2, LAMR1, VBP1 and CUL2 belong to the group of genes exhibiting the most discriminating differential expression ratio in uveal melanomas cell lines compared to the expression ratio of the normal melanocytes." (PMID 14612903, 2003). "Four candidate tumour markers, Laminin Receptor 1, Endothelin 2, Von Hippel Lindau Binding protein 1 and Cullin 2, have been selected from genes that were differentially expressed in the uveal melanoma cell lines compared to the normal uveal melanocytes." (PMID 14612903, 2003). "An important role in uveal melanoma development is now suggested for Laminin Receptor 1 (LAMR1), Endothelin 2 (ET2), Von Hippel Lindau Binding Protein 1 (VBP1) and Cullin 2 (CUL2) genes, since their expression levels discriminate between two classes of uveal melanoma." (PMID 14612903, 2003).
tumor (30 papers, 2003 to 2026). "CUL2, which is associated with response to the hypoxic environment and activation of tumor immunity, has been identified in association with CRO in nine independent case-control series." (PMID 32117227, 2020). "MLN4924 treatment rapidly blocked neddylation of cullin 1 and cullin 2, two tumor-associated cullin family members." (PMID 27223074, 2016). "CUL2 forms a ubiquitin ligase enzyme complex as a skeleton molecule and plays essential roles in tumor blood vessel production, cellular activity, immune escape, cell proliferation, and tumor malignant behavior." (PMID 39833662, 2025). "It is well understood that E7 induces the proteasomal degradation of various tumor suppressors, such as pRb and mediator of cell motility 1, by interacting with the CUL2 ubiquitin ligase complex." (PMID 38226814, 2024). "Recently, it has been reported that PRAME forms a complex with p14/alternate reading frame (ARF) (CDKN2A), a well-established tumor suppressor, as well as with Cullin 2 RING E3 ligases." (PMID 38132219, 2023). "VHL protein, a tumor suppressor, is part of the cullin-2 (CUL2) ring complex that functions in the ubiquitin ligase of fragmented forms of TDP-43." (PMID 36439561, 2022). "IHC staining confirmed that xenograft tumor tissues with suppression of CUL2 displayed much lower Ki-67 indexes than the controls, suggesting that CUL2 acts as an oncogene through its pro-proliferation activity during HPV16 induced cervical carcinogenesis." (PMID 27153550, 2016). "Those CUL2-suppressing and control cells were subcutaneously injected into the right-side and left-side axilla of 8 nude mouse, respectively, and tumor size was monitored every 3 days for a period of 4 weeks." (PMID 27153550, 2016). "Cul2 is part of the VHL tumor suppression complex that ubiquitinates HIF1α; the disruption of HIF1α has been found to improve the insulin sensitivity and decrease adiposity in mice." (PMID 24628878, 2014). "Among these were genes with tumor-suppressive activities such as CUL2, CTNNA3, and RNF8 (ST2B)." (PMID 40723280, 2025). "Increasing studies have shown that over-expression of CUL2 can prevent tumor growth and control sensitivity to cisplatin, which could constitute a new therapeutic target for cancer." (PMID 39689117, 2024). "It was proved that Circ-CUL2 exerted its tumor suppressive influence via miR-888-5p/RB1CC1 axis." (PMID 35068326, 2022). "Mouse model also revealed a slowed growth of tumor transplanted by cells with CUL2 knockdown." (PMID 27153550, 2016). "Transcriptomic profiling of TCGA datasets revealed significant up-regulation of CUL1, CUL2, CUL4A, CUL4B, CUL5, CUL7, and CUL9 in tumor tissues, with higher expression correlating with advanced stage and poorer survival, particularly for CUL5 and CUL7." (PMID 42021323, 2026). "VHL is a tumor suppressor, acting as a substrate adaptor, consisting of the VHL E3 ubiquitin ligase complex together with Cullin-2 (Cul-2), Elongins B/C (ELB/ELC), and RING-box." (PMID 39748950, 2024). "CUL2, an important member of the Cullin-RING ubiquitin E3 ligase family, promotes tumor angiogenesis, regulates cell motility, induces tumor immune escape, and regulates cell proliferation." (PMID 38495497, 2024). "In conclusion, the molecular chaperone activity of PRDX1 to bind to CUL2 was at least as important as the peroxidase activity, providing new insights into the role of PRDX1 for drug design to inhibit CRC progression by modulating anti‐tumor immunity." (PMID 41306557, 2025). "The expression patterns of the genes VBP1 and CUL2 exhibited a small overlap in both assays and revealed no elevated expression levels in the primary tumour samples." (PMID 14612903, 2003).
cancer (22 papers, 2013 to 2025). A tumor composed of atypical neoplastic, often pleomorphic cells that invade other tissues. "PRAME is a CUL2 ubiquitin ligase subunit that is normally expressed in the testis but becomes aberrantly overexpressed in many cancer types in association with aneuploidy and metastasis." (PMID 37162820, 2023). "Dysregulation of the cullin-2-based E3 ubiquitin system is associated with numerous human diseases, including cancer, and was correlated with the prognosis of cancer patients." (PMID 31320996, 2019). "Dysregulation of cullin-2-based E3 ubiquitin system is associated with numerous human diseases, including cancer, and correlated with the prognoses of cancer patients." (PMID 26771237, 2016). "In addition, CUL2 gene mutations are common in multiple cancers with low mutation rates and CUL2 is closely related to the prognosis of some cancer's patients, some immune regulatory factors, TMB, MSI, MMR genes, and DNA methylation." (PMID 38787355, 2024). "Thus, it is likely that Myeov2 also regulates Cul2-type CRLs and its perturbation may cause several cancers." (PMID 23776465, 2013). "In the analysis of key genes co-expression, we found the four genes (CDC73/CDC123/B4GALT1/CUL2) are most relevant to the expression of key genes and also related to the occurrence of many cancers." (PMID 35111402, 2022). "Recently, as more SRSs are being discovered and more aspects of substrate recognition have been illuminated, insight into the relationship between Cul2-dependent SRSs and substrates provides a new area for cancer research." (PMID 27107416, 2016). "Since no CUL2 mutation was found to play a critical role in HIF-1α activation in several cancers, it is likely that HIF-1α loss of homeostasis in cancer is mediated primarily by deregulation of cullin expression rather than cullin point mutations." (PMID 29594129, 2018). "For instance, CUL2, RBX1, ELOB, and ELOC are known to interact with PRAME, a substrate-recognition subunit that is overexpressed in a variety of cancers, including HCC." (PMID 35664333, 2022). "To gain a pan-cancer perspective on alterations to these genes, we evaluated the DNA CN status of VHL, CUL2, RBX1, ELOC, and ELOB across 33 cancer types processed by TCGA." (PMID 35664333, 2022). "By using high-affinity polypeptide monobody binders of human SHP2 and a nanobody recognizing human ASC protein conjugated to the CUL2 substrate receptor VHL, we achieve near-complete proteolysis of endogenous SHP2 and ASC in human cancer cell lines." (PMID 28490657, 2017). "The expression level of six differentially expressed mRNAs (CUL2, HIF1A, RET, JAK1, STAT1, and BCL2) in the cancer pathway and two of their nearby lncRNA pairs (RP11-124O11.2 and lincRNA-TMEM30B-1) was verified by real-time quantitative RT-PCR (qRT-PCR)." (PMID 24672800, 2014). "Given that neddylation has been shown to modulate HIF via Cullin-2, MLN-4924, an adenosine monophosphate analog able to deneddylate cullin proteins, can act as a potent HIF stabilizer in vitro and in vivo, being also a viable tool in the treatment of cancer cells." (PMID 28536364, 2017).
infection (5 papers, 2009 to 2025). The state of being infected such as from the introduction of a foreign agent such as serum, vaccine, antigenic substance or organism. "Following Ecc15 infection, the Cul2-/-; ubi>eff OE flies displayed a survival rate close to that of the ubi > + flies, even though all of them survived well with PBS treatment." (PMID 40141268, 2025). "Consistently, overexpression of Cul2 alone benefited the fly immune defense against Ecc15 infection." (PMID 40141268, 2025). "Specifically, we demonstrated that SG inhibition is dependent on the BC box domain of CrPV-1A, which recruits the Cul2-Rbx1-EloBC complex, and acts in concert with an essential R146 residue to promote infection." (PMID 36455064, 2022). "Indeed, restoration of Cul2 expression rescued the decreases in AMP inductions in the Cul2 LOF flies after Ecc15 infection." (PMID 40141268, 2025). "However, when we monitored the fly survival rates after Ecc15 infection, we observed that the eff RNAi flies exhibited a decreased survivability, similar to that of the Cul2 RNAi flies." (PMID 40141268, 2025). "The S. marcescens-induced upregulations of Dpt, AttA, and CecA1 were again decreased in the Cul2 LOF mutant flies, corroborating the phenotype seen with Ecc15 infection." (PMID 40141268, 2025). "The cullin 2/5 proteins are key components of the E4-ORF6/E1B-55K-Ub ligase complexes of different Ad serotypes and provide a scaffold to mediate ubiquitin-dependent degradation of numerous antiviral host proteins during infection." (PMID 26814176, 2016).
bacterial infections (1 paper, 2025). "We demonstrated that loss-of-function of Cul2 led to a marked reduction in antimicrobial peptide induction following bacterial infection, which was associated with increased fly mortality and bacterial load." (PMID 40141268, 2025). "Taken together, our data emphasize the crucial role of Cul2 in orchestrating the effective host defense against bacterial infections in Drosophila." (PMID 40141268, 2025). "To address this issue, we first employed the Cul2 LOF mutant flies for bacterial infections and observed that these mutants exhibit a pronounced susceptibility to bacterial infection, including a reduced survival rate and a diminished expression of key AMPs downstream of the IMD signaling pathway." (PMID 40141268, 2025). "To determine whether Cul2 modulates the Drosophila antibacterial immune defense via the eff function, we conducted a series of bacterial infection assays using both genetic knockdown and overexpression approaches." (PMID 40141268, 2025). "By performing a series of genetic approaches, we assessed the impact of Cul2 on AMP production, bacterial clearance, and fly survival following bacterial infections." (PMID 40141268, 2025). "In detail, double RNAi combinations revealed that silencing of Cul2 in the eff RNAi genetic background failed to affect the Drosophila immune defenses upon bacterial infection." (PMID 40141268, 2025).
inflammation (1 paper, 2020). Aberrant reaction of the microcirculation characterized by movement of fluid and leukocytes from the blood into extravascular tissues. "This is the first depiction of the expression of UBD, UBE2L3, CUL2, and HSP5 genes in the colonic mucosa from patients with UC, suggesting that these genes could be involved in the pathogenesis of colonic inflammation in patients with UC." (PMID 32410873, 2020).
neurodegenerative disease (1 paper, 2016). A disorder of the central nervous system characterized by gradual and progressive loss of neural tissue and neurologic function. "In the context of neurodegenerative diseases, VHL interacts with DJ-1 and prevents HIF1α degradation by CUL2, which may partly explain the neuroprotective role of DJ-1 in Parkinson’s disease." (PMID 26751167, 2016).
CUL2 also shares sentences with these, for which no sentence is quoted: COVID-19 (3 papers); Crohn disease (2); dyslipidaemia (2); pancreatic ductal adenocarcinoma (2); adenocarcinoma (1); autism (1); autoimmune (1); Cervical (1); cervical squamous cell carcinoma (1); cholangiocarcinoma (1); chronic obstructive pulmonary disease (1); colitis (1); dilated cardiomyopathy (1); fatty liver disease (1); glioblastoma (1); Glucose intolerance (1); HCMV infection (1); head and neck cancer (1); HIV-1 infection (1); oligodendroglioma (1); psoriasis (1); retinoblastoma (1); ulcerative colitis (1); vascular tumors (1).